XRCC1 (X-ray repair cross complementing 1)
Diseases named in the same sentence as XRCC1 in open-access papers (continued):
Sharing a sentence is not in itself a finding about the gene and the disease.
tumor (continued). "We found that none of the XRCC1 Arg194Trp and Arg399Gln polymorphisms was significantly associated with tumor response." (PMID 24465544, 2014). "We found that the distribution of these allelic variants did not vary significantly according to the tumor site, except for the XRCC1 Gln allelic variants (P = 0.016)." (PMID 23894404, 2013). "Paired tumor tissue was used to estimate the frequency of allelic imbalance at the XRCC1 SNP." (PMID 21586140, 2011). "Three, we found that tumor genotype reflected germline genotype at the XRCC1 399 loci (19q13.2) in 90% of informative cases, suggesting germline DNA may be an appropriate surrogate of tumor genotype." (PMID 21586140, 2011). "We found that AI at this XRCC1 SNP is uncommon; this finding supports the use of germline DNA, which is far more accessible clinically, when attempting to use this SNP to predict therapeutic tumor response in the tumor using this SNP to therapy." (PMID 21586140, 2011). "Moreover, PD-1/PD-L1 expression and CD4+ intraepithelial lymphocytes (IELs) are associated with tumour progression in patients possessing the wild-type XRCC1, suggesting that XRCC1 expression is correlated with patient survival, tumour-infiltrating lymphocytes, and immune marker expression." (PMID 37679817, 2023). "Therefore, the expression and function of DPYD, TYMS, MTHFR, ERCC1, ERCC2, XRCC1, and GSTP1 may be influenced not only by genetic polymorphisms, but also by processes that are specific for the tumor tissue." (PMID 33429840, 2021). "The XRCC1 protein directly associates with polymerase beta, DNA ligase III, and poly (ADP-ribose) polymerase (PARP) in single-strand break-repair processes that may play a role in tumor cell sensitivity to 5-FU treatment." (PMID 23894404, 2013). "XRCC1 negative tumours were associated with platinum sensitivity (p<0.0001)." (PMID 23451157, 2013). "In addition, we assessed whether germline genotype may serve as a surrogate for tumor genotype at this XRCC1 SNP by examining allelic imbalance (AI)." (PMID 21586140, 2011). "The deep region of the tumor was accurately classified by sorting nexin-18 and beta-COP, while peptide YY (PYY), NID-1, and XRCC1 contributed weakly." (PMID 39195201, 2024). "Changes in several ECM components known to promote growth of tumour cells, such as the collagens COL1A1, COL1A2, and the MMP2 metalloprotease were also evident in XRCC1 KD cells, again reflecting an activated fibroblast phenotype." (PMID 29568385, 2018). "We showed that XRCC1 and ALDH2 mRNA levels are related and that a high XRCC1 mRNA/low ALDH2 mRNA ratio seems to be accompanied by tumour aggressiveness." (PMID 30088263, 2018). "This evidence indicates that XRCC1 KD CAF-like cells are hypersensitive to midostaurin, which is also effective in preventing their tumour promoting capability." (PMID 29568385, 2018). "Our results from this study show that BZA treatment is highly effective in reducing XRCC-1, ERCC-1 and survivin expression in tumor cells." (PMID 28978005, 2017). "Higher protein expression levels in tumour tissue were identified for MLH1, MPG, Polβ and XRCC1, respectively, in 79%, 59%, 56% and 57% of all cases." (PMID 28903334, 2017). "After adjusting for potentially prognostic factors, XRCC1 rs25489 and OGG1 rs1052133 had a significant impact on primary tumor efficacy at the end of radiotherapy." (PMID 29108254, 2017). "Univariate analysis demonstrated that significant association was observed between mOS and PS (P < 0.001), gender (P = 0.007), tumor differentiation grade stage (P = 0.005), JWA (P < 0.001) or XRCC1 (P < 0.001) mRNA expression in the whole cohort." (PMID 25925371, 2015). "ATM, ATR, DNA-PKcs and XRCC1 protein expressions were investigated in a Cox multivariate model that was also adjusted for FIGO stage, grade, and residual tumour burden after surgery, chemotherapy and CA-125 response." (PMID 26674120, 2014).
tumor (continued). "XRCC1 (AUC=0.847), SOX4 (AUC=0.985), and HOXD9 (AUC=0.767) indicated that these three genes could be ideal biomarkers to distinguish LGG from non-tumor tissues." (PMID 38217545, 2024). "According to that, we hypothesized that miR-92a-3p triggers EMT in tumor cells through the activation of β-catenin, leading to the upregulation of DPYD, TYMS, MTHFR, ERCC1, ERCC2, and XRCC1 expression." (PMID 38659583, 2024). "XRCC1 and WDR5 were not present in healthy control tissues, suggesting their specific tumor-associated roles." (PMID 39195201, 2024). "In addition, FOXM1 is an upstream regulator of various DNA damage repair genes such as XRCC1, BRCA2, RAD51, BRIP1 and NBS1, thereby enabling the tumor cells to resist the action of the genotoxic agents." (PMID 37025658, 2023). "Furthermore, the levels of DNA repair proteins (HMGB1, LIG, and XRCC1) and DNA excision repair protein (ERCC-3, a tumor-preventing gene) were detected by western blotting." (PMID 35473479, 2022). "This phenomenon may constitute an underexplored mechanism of chemoresistance in tumor cells under EMT, implying that expression of the genes DPYD, TYMS, MTHFR, ERCC1, ERCC2, XRCC1, and GSTP1 may be modulated EMT-TFs." (PMID 33429840, 2021). "However, it is not until pSTAT3 levels become dysregulated that sustained increases in XRCC1 expression and subsequently changes in BER and SSBR would be observed, contributing to chemoresistance and tumor aggressiveness." (PMID 34067421, 2021). "However, there was a non-significant difference between SC/ASC and AC in other clinicopathological features including tumor differentiated degree, tumor size, TNM stages, receiving surgical methods, and XRCC1 positive expression (all P > 0.05)." (PMID 32426369, 2020). "On the other hand, imbalancing BER at later steps (e.g. XRCC1 overexpression) would not significantly alter tumour response to 5-FU or TMZ, since no energy metabolism disruption was observed in XRCC1 overexpressing cells upon 5-FU or TMZ treatment." (PMID 28903334, 2017). "By using multivariate Cox proportional hazards models with backward stepwise exclusion, XRCC1 (p = 0.002), FEN1 (p = 0.001), pol β (p = 0.032), BRCA1 (p = 0.040) and tumour stage (p < 0.0001) remained significant independent predictors for BCSS after controlling for adjuvant chemotherapy." (PMID 26267318, 2015). "For additional non-TYMS genes analyzed, XRCC1 (c.1196G>A, rs25487) and MDR1 (c.3435C>T, rs1045642) showed a potential association to tumor response." (PMID 25232828, 2014). "In the current study we therefore explored if patient stratification could be achieved based on XRCC1, ATM, DNA-PKcs and ATR expression statuses in tumours." (PMID 26674120, 2014). "In addition, we identified XRCC1 (AUC=0.847), SOX4 (AUC=0.985), and HOXD9 (AUC=0.767) as three molecules that could be ideal biomarkers to distinguish LGG from non-tumor tissues." (PMID 38217545, 2024). "In contrast, only 17% of patients with XRCC1-negative tumours were resistant to platinum drugs." (PMID 37679817, 2023). "In addition, reduced XRCC1 levels has been found in HNC patients compared to normal controls, suggesting XRCC1 might play a tumor suppressive role in HNSCC." (PMID 33049713, 2020). "Our bioinformatics analyses indicate that the CAF-like cells generated by depleting XRCC1 display a gene expression profile that is virtually indistinguishable from tumour stroma samples, whereby XRCC1 downregulation negatively correlates with expression of CAF markers." (PMID 29568385, 2018). "Although the rs1799782 locus of the XRCC1 gene was detected, the rs1801157 locus of the SDF-1ɑ gene and genotype were not correlated with tumor location or stage." (PMID 38337001, 2024).
tumor (continued). "Similarly, women with the XRCC1-399 Gln/Gln genotype presented with a significantly increased risk for grade II and grade III tumours (OR 1.80, 95% CI 1.06–3.07) when compared to those with the Arg/Arg genotype, while no increase was seen for grade I tumours (OR 1.10, 95% CI 0.75–1.62)." (PMID 16280050, 2005). "In 2/10 unmatched tumor tissue samples, allelotyping data could be obtained for ERCC1 but not for ERCC2 and XRCC1, probably due to poor FFPE DNA quality." (PMID 20066159, 2009). "While the significance of XRCC1 elevations in PDAs not known, we reasoned that pharmacological inhibition of BER in PDA, instead of segregating PDA patients based on XRCC1 expression, would be the most practical strategy to enhance tumor specificity and efficacy of ß-lap (ARQ761)." (PMID 26602448, 2015).
infection (6 papers, 2010 to 2025). The state of being infected such as from the introduction of a foreign agent such as serum, vaccine, antigenic substance or organism. "We also investigated the mRNA relative expression of PARP-1, OGG1, and XRCC1, a protein involved in repairing DNA single-strand breaks, after 6 h of infection." (PMID 33826673, 2021). "Based on this finding and on previous studies showing reversal of the phenotypic effects of XRCC1 deletion by low-level XRCC1 expression, we began all experiments within 1 week of infection." (PMID 20705543, 2010). "We hypothesize that targets identified in our iPOND analysis, such as GINS3, TOP2A and XRCC1, may play a role in maintaining host replisome stability as wtAAV2 mono-infection progresses long-term." (PMID 40825038, 2025). "Cre-ad infection of Xrcc1flox/flox myoblasts at 3 and 6 h post-low-serum exposure led to a complete block in differentiation, similar to the results obtained for shRNA targeting of the Xrcc1 gene and Cre-mediated deletion of Xrcc1 in cycling myoblasts." (PMID 27462438, 2016). "Host proteins enriched at cellular replication forks during infection included DNA processing factors such as GINS, TOP2A, PRIM1/2, RPA2 and XRCC1; DDR signaling proteins such as CSNK2A1/3; cell cycle regulator proteins such as TFDP2 and SFN1; as expected for cells undergoing replication stress." (PMID 40825038, 2025). "Higher levels of XRCC1 mRNA in HeLa cells and AC16 cells after 6 h of infection were observed." (PMID 33826673, 2021).
neurodegenerative disease (3 papers, 2012 to 2021). A disorder of the central nervous system characterized by gradual and progressive loss of neural tissue and neurologic function. "The importance of XRCC1 is illustrated by the observations that deletion of this gene in mouse is embryonic lethal and that hereditary mutations in human XRCC1 result in progressive neurodegenerative disease." (PMID 34102106, 2021).
neurological disease (3 papers, 2021 to 2024). "Intriguingly, the deletion and/or inhibition of PARP1 greatly reduces or prevents these pathologies in an Xrcc1-defective mouse model of SSB-associated neurological disease, highlighting excessive/aberrant PARP1 activity as a source of SSB-induced neuropathology." (PMID 34811483, 2021). "This is an exciting finding, because it supports the possibility that PARP inhibition might provide a therapeutic approach for the treatment of XRCC1‐defective, and possibly other, neurological diseases." (PMID 33932076, 2021).
head and neck tumors (2 papers, 2018 to 2024). "Three articles published results on the relationship between the Arg194Trp polymorphism in the XRCC1 gene and clinical outcomes in patients with head and neck tumors." (PMID 38473311, 2024).
adenocarcinoma (1 paper, 2025). A common cancer characterized by the presence of malignant glandular cells. "Studies of the XRCC1 Gln399Gln polymorphism of the Polish population showed that the risk of death from lung malignancy was higher in adenocarcinoma patients with XRCC1 Gln/Gln genotypes, although their frequency was low." (PMID 40650316, 2025).
cardiovascular disease (1 paper, 2007). "The association of XRCC1 SNPs and cardiovascular disease has also received attention." (PMID 17242676, 2007).
genetic disease (1 paper, 2021). "Similar results were observed when we employed primary patient fibroblasts from XRCC1-mutated disease, suggesting that increased PARP1 trapping during BER is also a feature of this human genetic disease." (PMID 34102106, 2021).
kidney disease (1 paper, 2018). "The association between DNA repair genes (XPD and XRCC1) and kidney disease is not commonly investigated, and with the exception of the study reviewed in this publication, has only been investigated previously in a Turkish population." (PMID 30340464, 2018).
neurodevelopmental disorder (1 paper, 2024). A behavioral and cognitive disorder with onset during the developmental period that involves impaired or aberrant development of intellectual, motor, or social functions. "Hereditary mutations in XRCC1 were shown in neurodevelopmental disorders and/or progressive neurodegeneration." (PMID 38782988, 2024).
XRCC1 also shares sentences with these, for which no sentence is quoted: Ataxia (5 papers); axonal neuropathy (3); basal cell carcinoma (3); pancreatic adenocarcinoma (3); skin reaction (3); ad (2); ataxia telangiectasia (2); endocervical adenocarcinoma (2); leukopenia (2); multiple myeloma (2); neutropenia (2); oral squamous cell carcinoma (2); Parkinson disease (2); pneumonitis (2); acute leukemia (1); Age-related cataract (1); alcohol (1); Alzheimer's disease (1); amyotrophic lateral sclerosis (1); anxiety disorder (1); ataxia-telangiectasia-like disorder 1 (1); ataxic disorders (1); Atrophy (1); Azoospermia (1); cataract (1); childhood acute lymphoblastic leukemia (1); chronic atrophic gastritis (1); chronic hepatitis B (1); Chronic Myeloid Leukemia (1); colorectal adenocarcinoma (1).
A further 53 diseases each share a sentence with XRCC1 in 1 paper.